GPR161 (G protein-coupled receptor 161)
Description:
G protein-coupled receptor that acts as a key inhibitor of the smoothened signaling pathway in primary cilia. Inhibits the smoothened signaling pathway in absence of hedgehog (DHH, IHH or SHH) by promoting formation of the transcription repressor form of GLI2 and GLI3 transcription factors. GPR161 activation triggers signaling via guanine nucleotide-binding protein G(s)/GNAS, mediating activation of adenylate cyclase activity and production of cAMP. Increased cAMP levels activate PKA, promoting PKA-dependent processing of GLI2 and GLI3 transcription factors, leading to formation of transcription repressor GLI2R and GLI3R, which repress expression of target genes. GPR161 also activates PKA by acting as a PKA-anchoring protein, which directly associates with type I PKA regulatory subunits (PRKAR1A and/or PRKAR1B), recruiting PKA followed by PKA-dependent processing of GLI2 and GLI3 transcription factors. In presence of hedgehog, GPR161 is removed from primary cilia by smoothened (SMO), preventing its activity and allowing activation of the smoothened signaling (By similarity). In contrast to the majority of G protein-coupled receptors, it is not activated by a ligand and it either acts as a constitutively active receptor or as a mechanosensitive receptor. Involved in regulation of the smoothened signaling pathway during early neural tube development, forelimb formation, skeletal development, embryonic cerebellar development and forebrain development (By similarity). Involved in the saltatory migration of neurons during brain development by acting as a mechanosensitive receptor that senses mechanical forces generated by fluid shear stress (By similarity).
Synonyms: RE2
Tractability: Small molecule: a structure with a bound ligand is known; it belongs to a druggable protein family. Antibody: UniProt places it where antibodies can reach, with medium confidence; UniProt predicts a signal peptide or a membrane-spanning region; its Gene Ontology location is reachable by antibodies, with medium confidence. PROTAC: ubiquitination databases record sites on it.
Target class: Family A G protein-coupled receptor; Membrane receptor
Gene: Protein-coding gene on chromosome 1 (168,079,542 to 168,137,685, reverse strand). Ensembl gene ENSG00000143147.
Subcellular location: Cell projection, cilium membrane; Cell membrane
Subcellular location (Human Protein Atlas): Primary cilium; Primary cilium transition zone
Pathways (Reactome):
Signal Transduction: Hedgehog 'off' state; Hedgehog 'on' state
Gene Ontology:
Molecular function: G protein-coupled receptor activity; protein binding; signaling adaptor activity
Biological process: adenylate cyclase-activating G protein-coupled receptor signaling pathway; negative regulation of smoothened signaling pathway; cerebellum development; forebrain development; limb development; negative regulation of smoothened signaling pathway involved in dorsal/ventral neural tube patterning; regulation of neuron migration; skeletal system development; G protein-coupled receptor signaling pathway
Cellular component: non-motile cilium membrane; ciliary membrane; endocytic vesicle membrane; recycling endosome; membrane; plasma membrane
Genetic constraint (gnomAD): Loss-of-function variants: 25 observed, 40.86 expected, observed/expected ratio (o/e) 0.61, 90% interval 0.44 to 0.86. The upper end of that interval is the gene's LOEUF score, 0.86, which puts it in group 3 of 6, group 1 being the genes least tolerant of losing a copy. Missense variants: 506 observed, 667.08 expected, observed/expected ratio (o/e) 0.76, 90% interval 0.7 to 0.82. Synonymous variants: 266 observed, 271.92 expected, observed/expected ratio (o/e) 0.98, 90% interval 0.88 to 1.08.
Homologues: Orthologues: chimpanzee GPR161 (98% identical), macaque GPR161 (98% identical), rabbit GPR161 (94% identical), dog GPR161 (93% identical), pig GPR161 (93% identical), mouse Gpr161 (93% identical), rat Gpr161 (93% identical), guinea pig GPR161 (92% identical), tropical clawed frog gpr161 (69% identical), zebrafish gpr161b (65% identical), zebrafish gpr161a (62% identical). Paralogues in human: DRD5 (19% identical), HRH2 (18% identical), DRD1 (17% identical), HTR1A (17% identical), HTR4 (17% identical), CHRM5 (16% identical), CHRM3 (16% identical), CHRM2 (16% identical), DRD3 (15% identical), CHRM1 (15% identical), HRH1 (15% identical), TAAR6 (15% identical), and 13 more.